GLIS3 (GLIS family zinc finger 3)
Diseases named in the same sentence as GLIS3 in open-access papers (continued):
Sharing a sentence is not in itself a finding about the gene and the disease.
Pancreatic cysts (1 paper, 2016). A cyst of the pancreas that possess a lining of mucous epithelium. "Consistent with previous observations, analysis of Glis3-KO2 mice showed that loss of Glis3 function results in the formation of pancreatic cysts supporting a regulatory role for Glis3 in pancreatic duct morphogenesis." (PMID 27270601, 2016). "Consistent with previous findings in Glis3zf/zf mice, the expression of Ins1 and Ins2 was also greatly decreased in Glis3KO2 pancreas and loss of Glis3 expression induced development of pancreatic cysts suggesting a regulatory role in pancreatic duct morphogenesis." (PMID 27270601, 2016).
Patent ductus arteriosus (1 paper, 2015). In utero, the ductus arteriosus (DA) serves to divert ventricular output away from the lungs and toward the placenta by connecting the main pulmonary artery to the descending aorta. "It is likely that the patent ductus arteriosus observed in patients 3a and 10 was due to prematurity rather than to an abnormality in GLIS3 function." (PMID 26259131, 2015).
prostate tumors (1 paper, 2023). "On the other hand, we focused on six genes (COL4A5, GLIS3, NPR1, OSR2, PLAGL1 and RSPO3) that were significantly downregulated in human prostate tumors as well as upregulated in DU145-R427 cells, suggesting that these genes might negatively interfere with prostate tumorigenesis." (PMID 38045004, 2023).
schizophrenia (1 paper, 2024). A major psychotic disorder characterized by abnormalities in the perception or expression of reality. "For example, the direction of effect for the GLIS3 cis instrument switched, implying a positive association with schizophrenia." (PMID 39263363, 2024).
sensorineural hearing loss (1 paper, 2024). "Among 20 TFs, Zbtb18 participated in sensorineural hearing loss (SNHL), Insm1, Foxo4, Tcf4, and Glis3 were involved in controlling the differentiation of IHCs and OHCs." (PMID 38015350, 2024).
Splenic cyst (1 paper, 2015). A closed sac located in the spleen. "We report the first patient with a GLIS3 mutation to present with a splenic cyst (patient 3b)." (PMID 26259131, 2015).
cancer (10 papers, 2010 to 2026). A tumor composed of atypical neoplastic, often pleomorphic cells that invade other tissues. "Chromosomal rearrangements of the GLIS3 locus have also been implicated in various cancers." (PMID 41369402, 2025). "GLIS3 is essential for controlling numerous physiological processes and has been linked multiple diseases, including neonatal diabetes, glaucoma, polycystic kidney disease, neurological disorders, congenital hypothyroidism, and cancer." (PMID 36923439, 2023). "Comparing GLIS3 expression in normal tissues and tumor samples from the TCGA and GTEx databases, we discovered that GLIS3 expression differed significantly in the majority of cancer types." (PMID 36923439, 2023). "The expression pattern of GLIS3 varies significantly in different types of cancers." (PMID 36923439, 2023). "Additionally, the association among circGLIS3, miR-449c-5p, CAPG, and GLIS3 was validated in both NHAs and GBM cells, indicating that it was not a cancer-specific relationship." (PMID 36114444, 2022).
tumor (6 papers, 2016 to 2026). "Univariate analysis revealed that age, TMN classification, pathologic stage, Primary therapeutic outcome, and Residual tumor are linked with GLIS3 expression level and OS (P<0.05)." (PMID 36923439, 2023). "Also, NK cells, which are highly associated with GLIS3 expression, impact on immunotherapy, and targeting NK cells may improve anti-tumor immune responses." (PMID 36923439, 2023). "Among immune cells, macrophages demonstrated a stronger connection with GLIS3 expression (P<0.001) M1-type macrophages can destroy tumor cells and protect against pathogen invasion, but M2-type macrophages primarily promote tumor growth, invasion, and metastasis." (PMID 36923439, 2023). "From this, we can prove that GLIS3 may alter tumor immunology and may be a potential immunotherapy treatment target, instead of a simple prognostic biomarker." (PMID 36923439, 2023).
renal disease (5 papers, 2015 to 2024). "However, some patients (including our patient) with mutations in GLIS3 did not develop renal disease." (PMID 28253873, 2017). "However, whether GLIS3 leads to other kidney diseases even ESRD remains room for further research." (PMID 36967395, 2023). "However, some patients with mutations in GLIS3 did not develop renal disease." (PMID 26259131, 2015).
infection (2 papers, 2020 to 2022). The state of being infected such as from the introduction of a foreign agent such as serum, vaccine, antigenic substance or organism. "Of note, three of the four genes that were significantly regulated in all investigated conditions showed lessened induction upon concomitant infection and Smh1 expression (IL-1β, GLIS3, and MIR3142HG), while down-regulation of the fourth factor (RGS4) is accentuated by Smh1 expression." (PMID 36411449, 2022). "Other transcripts that we previously reported as being β-cell specific, including PCSK1 and MAFB, and GLIS3 and CASR, all decreased with infection." (PMID 32093375, 2020).
Cardiovascular disease (1 paper, 2024). "Among these, 10 regions, proximal to or within the genes OVAAL, BMP3, RIOK1, AC096553.5, MCPH1, KCNU1, GLIS3, TUT7, TRIB3, and SYNDIG1, represent novel associations with MI and have not been previously linked to Cardiovascular disease (CVD)-related traits." (PMID 38725839, 2024).
GLIS3 also shares sentences with these, for which no sentence is quoted: Osteopenia (3 papers); thyroid dysgenesis (3); athyreosis (2); atrial septal defect (2); cerebellar agenesis (2); ependymoma (2); IPEX syndrome (2); neurological disorders (2); osteoarthritis (2); thyroid cancer (2); ) channelopathies (1); acute megakaryoblastic leukemia (1); alcohol dependence (1); and kidney failure (1); Anorexia (1); atherosclerosis (1); autosomal dominant polycystic kidney disease (1); cardiac disease (1); Cerebellar hypoplasia (1); cholestasis (1); Cholestatic liver disease (1); ciliopathy (1); colon cancer (1); cutaneous melanoma (1); deafness (1); dental caries (1); diabetic nephropathy (1); endocrine disorders (1); enterovirus infection (1); Epiphyseal dysplasia (1).
A further 34 diseases each share a sentence with GLIS3 in 1 paper.